MARCO (macrophage receptor with collagenous structure)
Diseases named in the same sentence as MARCO in open-access papers (continued):
Sharing a sentence is not in itself a finding about the gene and the disease.
tumor (continued). "The author indicated that IL-15 production induced by anti-MARCO locally in the tumor and possibly the draining lymph node will support the proliferation, migration, and cytotoxic capacity of NK cells." (PMID 34177887, 2021). "Given the negative role of MARCO in other cancers, we chose to focus on these MARCO+ macrophages and their impact on the tumor microenvironment." (PMID 34011400, 2021). "Here, we show that MARCO+ macrophages appear to be recruited from the blood via the upregulation of a set of factors secreted by tumor cells, including CSF1 and TGF-β." (PMID 34011400, 2021). "One important question for the potential targeting of MARCO+ macrophages is where they originate from and how they are recruited to the tumor." (PMID 34011400, 2021). "For example, in breast and colon cancer and melanoma models, by reprograming the tumor-associated macrophage population to a proinflammatory phenotype and increasing tumor immunogenicity, anti-MARCO monoclonal antibodies can inhibit tumor progression." (PMID 34925511, 2021). "These spatially informed findings support the GSEA characterization of MARCO+ macrophages as residing in the hypoxic tumor core." (PMID 34011400, 2021). "Next, we compared the expression of MARCO between tumor tissues and control tissues across solid tumors." (PMID 34778091, 2021). "In this manuscript, we have characterized the role of MARCO as a marker of pro-tumor macrophages in GBM." (PMID 34011400, 2021). "In this work, we utilized single-cell RNA sequencing to identify a pro-tumor subpopulation of macrophages characterized by MARCO expression." (PMID 34011400, 2021). "Gene set enrichment analysis revealed upregulation of gene signatures related to epithelial–mesenchymal transition, glycolysis, angiogenesis, and hypoxia in MARCO-expressing macrophages localized in the tumor core." (PMID 34948178, 2021). "Only a few macrophage genes such as PPARG, MSR1/CD204, and MARCO were downregulated in TAMs compared to non-tumor macrophages in our dataset." (PMID 33918618, 2021). "Antibody-mediated targeting of MARCO on TAMs was shown to repolarize macrophages; reduce tumor growth and metastasis; and enhance the effect of CTLA-4 ICB in murine models of mammary cancer, melanoma, and colon carcinoma." (PMID 33924237, 2021). "Macrophages from the tumor core had higher MARCO expression than those taken from the tumor periphery (p < 0.001, n = 1846 cells; Mann-Whitney U test)." (PMID 34011400, 2021). "As the IL-37/IL-37R signaling axis is upstream of MARCO-mediated tumor promotional programs of TAMs, it represents a therapeutic target for repolarization." (PMID 33924237, 2021). "Since hypoxia can polarize macrophages toward a pro-tumor phenotype, we also investigated if appropriate antitumoral responses were downregulated within MARCO+ macrophages." (PMID 34011400, 2021). "By contrast, decreased MARCO expression by macrophages is correlated with tumor progression and poor prognosis in HCC." (PMID 34778091, 2021). "In doing so, we identify a novel pro-tumor macrophage marker in GBM (MARCO) validated by immunofluorescence imaging." (PMID 34011400, 2021). "In line with this, targeting the pattern recognition receptor MARCO can alter Mφ polarization and result in reduced tumor growth." (PMID 31825135, 2020). "Recent reports have recognized MARCO as a potential therapeutic target that is often overexpressed and involved in tumor microenvironment composition and promote poor prognosis across multiple cancer types." (PMID 32847614, 2020). "Co-staining of PD-L1, MARCO, and CD68 revealed MARCO+ TAMs are in direct contact with PD-L1+ tumor cells and demonstrated co-localization of MARCO and PD-L1 in TAMs." (PMID 33194645, 2020). "Treatment with antibodies targeting MARCO resulted in reduced tumor growth and inhibition of metastasis and a switch to a more proinflammatory macrophage phenotype." (PMID 31805946, 2019).
tumor (continued). "Due to its functions and interactions, MARCO has been put forward as a potential novel immunotherapy target and it was recently shown to reduce tumour growth in mouse models of cancer as well as adding to the effect of checkpoint therapy." (PMID 28673320, 2017). "We found that in addition to nuclear HO-1 in cancer cells in tumor xenografts, HO-1 is also expressed in stromal cells, specifically in the cytoplasm of MARCO positive macrophages in tumors." (PMID 26418896, 2015). "Genome-wide gene expression profiling of DC pulsed with tumor cell lysate revealed MARCO as the most upregulated gene." (PMID 25089703, 2014). "MARCO-/- DCs that were pulsed with tumor lysate demonstrated a significantly higher migratory ability than WT DC." (PMID 23840879, 2013). "We have previously shown that exposure of tumor lysate-pulsed DCs with an anti-MARCO antibody enhanced DC migration to draining lymph nodes." (PMID 23840879, 2013). "WT DCs express MARCO and MARCO expression is upregulated after exposure to either tumor lysate or LPS." (PMID 23840879, 2013). "We have developed MARCO knockout mice and examined the phenotype and efficacy of DCs generated from the bone marrow of these mice at inducing anti-tumor immunity in a murine B16 melanoma model." (PMID 23840879, 2013). "We have previously demonstrated upregulated macrophage receptor with collagenous structure (MARCO) expression in DCs pulsed with LPS or tumor lysates." (PMID 23840879, 2013). "T cells from WT mice immunized with tumor lysate-pulsed MARCO-/- DCs and then restimulated in vitro with tumor lysate-pulsed MARCO-/- DCs produced the highest levels of IFN-γ (p<0.001 compared to all other groups)." (PMID 23840879, 2013). "Mice treated with MARCO-/- DCs demonstrated delayed tumor growth (p<0.05 compared to other treatment groups)." (PMID 23840879, 2013). "We have reported the upregulation of MARCO, a member of the class A scavenger receptor family, on the surface of murine and human dendritic cells (DCs) pulsed with tumor lysates." (PMID 23840879, 2013). "To test the therapeutic efficacy of MARCO-/- DC treatment on tumor growth, we first injected B16 tumor cells s.c. into C57BL/6 mice." (PMID 23840879, 2013). "The use of an anti-MARCO antibody further reduced tumor volume in wild-type mice." (PMID 42049706, 2026). "Collectively, our findings provide strong evidence that MARCO downregulating antibody significantly enhances the anti-tumor immune response of anti-PD-1 immunotherapy by suppressing MDSC differentiation, altering TAM properties, and promoting the infiltration of CD8+ T cells and NK cells." (PMID 40695812, 2025). "Tumor volume analyses demonstrated that single anti‐PD‐1 mAbs showed moderate therapeutic effects; but when anti‐MARCO antibody was combined with anti‐PD‐1 therapy treatment, it might dramatically slow tumor development." (PMID 41117057, 2025). "We also identified MARCO as TAM‐enriched inhibitor of neoantigen cross‐presentation in ICB‐resistant RCCs, and demonstrated the therapeutic efficacy of targeting MARCO to recover tumor recognition and generate effective antitumor immunity in the ICB non‐responsive malignancies otherwise." (PMID 41117057, 2025). "Therefore, we next focus on MHC‐I expression on MARCO+ TAMs to investigate their role in tumor antigen cross‐presentation." (PMID 41117057, 2025). "One critical observation from this study was the significantly remodelled CD8+ T cells activation and development in ICB‐resistant RCCs mediated by MARCO+ TAMs, resulting in significant reduction of tumor‐killing GZMK+CD8+ Tem cells as well as accumulation of tumor‐resident ZNF683+CD8+ Trm cells." (PMID 41117057, 2025). "The results showed that MARCO gene knockout prevented tumor growth." (PMID 40695812, 2025). "Previous studies have reported that targeting MARCO antibodies has anti-tumor effects." (PMID 40695812, 2025).
tumor (continued). "Our research sheds light on the mechanisms by which MARCO governs MHC‐I molecules to alter TAMs' capacity for antigen cross‐presentation, suggesting a potential therapeutic target for RCC by modulating tumor‐associated macrophage reprogramming and restoring immune surveillance." (PMID 41117057, 2025). "While the mechanism of MARCO is unknown, its upregulation has been noted to be a likely immune evasion mechanism from tumor cells." (PMID 41301877, 2025). "We also observed individual tumor cells traveling through MARCO+ medullary sinuses." (PMID 41249124, 2025). "Collectively, our findings provide strong evidence that MARCO inhibition significantly enhances the anti-tumor immune response of anti-PD-1 immunotherapy by suppressing MARCO expression and MDSC differentiation, altering TAM properties, and promoting the infiltration of CD8+ T cells and NK cells." (PMID 40695812, 2025). "In the meantime, MHC‐I blocking could partly hinder the recovery of tumor‐infiltrating CD8+ CTLs (both IFN‐γ+CD8+ CTLs and GZMB+CD8+ CTLs) caused by MARCO‐knockdown TAMs, which is consistent with the in vitro findings." (PMID 41117057, 2025). "MARCO is a scavenger receptor on macrophages, marking a pro-tumor subset." (PMID 41346390, 2025). "Conversely, blocking MARCO restored their activity towards tumor cells." (PMID 38245882, 2024). "Interestingly, most CIDGS-related genes, such as XRCC6, ST13, PES1, EFHD2, APOL2, ACTR2, and CDCP1, were markedly upregulated in HNSCC tumor samples, whereas several other genes, such as MARCO, MRC1, and CD83, were upregulated in healthy samples." (PMID 38666027, 2024). "Recently, research revealed that MARCO+ TAMs exhibit a perivascular macrophage phenotype and that targeting MARCO-expressing macrophages can suppress the capability of MARCO+ TAMs to support tumour vascularization and activate natural killer (NK) cell killing via TNF-related apoptosis ligands only." (PMID 38303024, 2024). "MARCO was found to be co-regulated with IFI27 expression and exhibited a similar parameter profile for the multivariate Cox proportional hazards model, suggesting that the detection of MARCO in tumor tissue would limit the impact of TGFB2 knockdown for OS improvements in PDAC patients." (PMID 39457004, 2024). "MARCO is another SR that can carry out some antitumor functions via phagocytosis of tumor cells." (PMID 39516356, 2024). "Genes such as MARCO, FN1, ACE, and CD163L1 are likely associated with the immunoregulatory functions of M2 macrophages, which typically promote tissue repair, anti-inflammatory responses, and support tumor growth." (PMID 39697346, 2024). "Cluster 2 may consist of pro-tumor macrophages with the specific expression of MARCO and PLAUR (expressing e.g., CTSL, MARCO and PLAUR) and the proportion was significantly increased compared with N group." (PMID 37153595, 2023). "The upregulated expression of MARCO at time of PD in our patients may represent a greater infiltration of immunosuppressive and tumor promoting TAMs at the time of PD." (PMID 37624862, 2023). "Importantly, increased levels of MARCO-positive myeloid cells within the TME predict tumor progression and poor outcomes." (PMID 35399717, 2022). "Since MARCO is conserved between humans and mice, we hypothesize that targeting MARCO in humans could remodel the suppressive environment and reduce the anti-tumor responses to increase the efficacy of immunotherapy in PDAC." (PMID 36310582, 2022). "In the current study, we investigated whether MARCO is a marker for human PDAC tumor progression and its potential as a therapeutic target." (PMID 36310582, 2022). "In vitro, TAMs suppress tumor development utilizing MARCO to phagocytose cancer cells." (PMID 36686729, 2022).
tumor (continued). "We compared the DEGs between macrophages from HB tumor tissue and adjacent non-tumor liver, and found that attenuated expression of the scavenger receptor, MARCO, distinguished macrophages found in tumors (MARCOLow) from those isolated from adjacent normal liver (MARCOHi)." (PMID 36008377, 2022). "To investigate whether PDAC tumor cells were able to promote MARCO expression, we co-cultured naive macrophages with PDAC cell lines with different characteristics and assessed their phenotype and function." (PMID 36310582, 2022). "Several studies on clinical material revealed tumor-supporting phenotype of MARCO-expressing TAMs." (PMID 36686729, 2022). "However, while a marker of immunosuppressive macrophages, MARCO engagement led to the expression of the pro-inflammatory genes Tnf, Il1b, and Nos2, leading to reduced primary tumor growth and metastases." (PMID 34572013, 2021). "MARCO expression is induced by tumor-derived supernatant, IL-10, hypoxic conditions and IL-37." (PMID 34572013, 2021). "MARCO mean expression in macrophage cells also significantly correlated with the mesenchymal signature score in tumor cells from the same sample (p = 0.0084, n = 41 patients, Spearman correlation; see the “Methods” section), while anticorrelating with the proneural signature (p = 0.047)." (PMID 34011400, 2021). "Scavenger receptor MARCO, which is expressed on a specific subpopulation of TAMs in the tumor." (PMID 34177887, 2021). "Similarly, high MARCO expression in tumor tissues was positively correlated with high ECOG PS (P = 0.002), high TNM stage (P = 0.002), and low histopathological grading (P = 0.010)." (PMID 34778091, 2021). "Interestingly, anti-MARCO treatment results in repolarization of the M2-like anti-inflammatory TAM population to M1-like proinflammatory TAMs that increase tumor immunogenicity." (PMID 34476174, 2021). "Further studies are required to uncover the roles of MARCO in distinct tumor types." (PMID 34778091, 2021). "We found a significant positive correlation of MARCO mean expression in macrophage cells with the corresponding normalized expression of these recruitment factors in tumor cells from the same sample (p = 0.008, n = 41 patients, Spearman correlation; see the “Methods” section)." (PMID 34011400, 2021). "Furthermore, we have performed scTHI (single cell Tumor-Host Interaction) to identify significantly activated ligand-receptor interactions between mesenchymal tumor cells and MARCO+ TAMs." (PMID 32847614, 2020). "Because macrophages and Kupffer cells in lung or liver express MARCO, MARCO may be involved in tumor progression via exosome uptake." (PMID 33311558, 2020). "We explore the transcriptional regulatory networks of mesenchymal-associated tumor-associated macrophages (MA-TAMs), which drive the malignant phenotypic state of GBM, and identify macrophage receptor with collagenous structure (MARCO) as the most highly differentially expressed gene." (PMID 32847614, 2020). "Targeting TAMs with anti-MARCO (suppressive TAM marker) antibody converted them to a pro-inflammatory phenotype that favored anti-tumor activity in multiple tumor types, adding another entry to the arsenal of therapies against TAMs in restructuring the immune response." (PMID 35310881, 2020). "Additionally, MARCO is also expressed by a subpopulation of TAMs with an M2-like immunosuppressive gene signature in the TME of both murine tumor models and in human cancer." (PMID 31805946, 2019). "Macrophages are recruited to the tumor via blood circulation or direct immigration to adjacent tumors from surrounding tissues which might explain the elevated plasma levels of MARCO observed here across all CRC stages." (PMID 31467500, 2019). "These TAMs could be polarized to an inflammatory phenotype by anti-MARCO antibody which promoted tumor immunogenicity." (PMID 30348985, 2018).
tumor (continued). "Further, the novel macrophage marker MARCO, which has been shown to be a target for immunotherapy, was found to be associated with poor prognosis in I-type but not PB-type tumours." (PMID 28673320, 2017). "High density of MARCO+ macrophages was significantly associated with poor prognosis in I-type but not in PB-type tumours (HR = 2.14 95% CI 1.03–4.44), and this association was only evident in patients treated with adjuvant chemotherapy." (PMID 28673320, 2017). "Presence of HO-1 in MARCO-positive macrophages may indicate the mechanism for regulation of tumor growth via enhanced polarization of macrophages towards a pro-angiogenic M2 phenotype." (PMID 26418896, 2015). "We next randomly selected 8 genes aberrantly expressed in HCCs that had aberrant DNA methylation (CR1, ESR1, PTPN13, and SOCS2) or SCNA (C8A, CXCL14, ITGA6 and MARCO) to validate the array-based results in an independent sample set consisting 47 HCCs and paired non-tumor specimens." (PMID 25965583, 2015). "Together, these data suggest that pharmacologically blocking MARCO could recover the tumor recognition capacity of TAMs and boost the efficiency of ICB treatment in RCC, making it a promising therapeutic strategy for the treatment of RCC, especially for the ICB‐resistant tumors." (PMID 41117057, 2025). "Given that MARCO+ TAMs suppress antitumor immunity of CD8+ CTLs by impairing tumor recognition, we hypothesized that restoring the antigen presentation process by MARCO blockade would likewise recover the tumor recognition by eliciting anti‐tumor activity and boost ICB therapeutic efficacy." (PMID 41117057, 2025). "However, there is evidence that indicates that tumor conditions MARCO+ macrophages exhibit MDSC-like features, raising the intriguing possibility that MARCO may contribute to the immunosuppressive phenotype of MDSCs." (PMID 40695812, 2025). "Based on these studies and our current results we hypothesize that reprogramming the immunosuppressive and lymphocyte-excluding myeloid cells through anti-MARCO treatment can be a potential approach to re-recruit immune effector cells to the tumor area and convert cold tumors into hot tumors." (PMID 36310582, 2022). "In addition, it has been found that targeting MARCO expression in M2 TAMs in mouse breast cancer, melanoma, and colon cancer can increase the infiltration of M1 type macrophages in tumor tissues, reduce M2 type macrophages, and block tumor growth and metastasis." (PMID 33224886, 2020). "An anti-MARCO monoclonal antibody was, thus, developed and was shown as having an anti-tumor activity in breast and colon carcinoma, and in melanoma models through reprogramming of TAMs populations to a pro-inflammatory phenotype and increasing tumor immunogenicity." (PMID 31547627, 2019). "First, we describe important subpopulations of profibrotic and pro-tumor macrophages, including SPP1+, MERTK+, TREM2+, and MARCO+ cells, using high-resolution spatial and single-cell omics technologies." (PMID 41939908, 2026). "High infiltration of both MARCO+ TAMs and CTSE+ tumor cells correlated with the poorest survival outcomes." (PMID 40507339, 2025). "For example, targeting the scavenger receptor MARCO on TAMs alters TAM polarization and, in turn, activates natural killer (NK) cells to kill the tumor." (PMID 40507854, 2025). "Further, MARCO blockade significantly facilitates ICB therapy in in vivo models by recovering tumor recognition and priming anti‐tumor CD8+ T cell responses." (PMID 41117057, 2025). "This potential connection between MARCO expression and MDSC warrants further investigation to elucidate its role in shaping the immunosuppressive tumor microenvironment." (PMID 40695812, 2025). "We further sorted MARCO+ and MARCO‐ TAMs from RCC tumor tissues and performed transcriptome analyses, which confirmed the downregulation of antigen‐presentation pathway and MHC‐I genes (HLA‐A and HLA‐B) in MARCO+ TAMs." (PMID 41117057, 2025).